ADAT3 (adenosine deaminase tRNA specific 3)
Description:
Non-catalytic subunit of the tRNA-specific adenosine-34 deaminase complex, composed of the ADAT2 catalytic subunit and the ADAT3 regulatory subunit, which deaminates adenosine-34 (the first, also called wobble position of the anticodon) to inosine in many tRNAs. Inosine-34 allows the decoding of 3 different nucleotides at the third position of mRNA codons, as inosine is able to pair with U, C, and A. Required for binding of the ADAT2-ADAT3 complex to tRNA through its N-terminus, which rotates with respect to the catalytic domain of the complex, formed by ADAT2 and the ADAT3 C-terminal domain, to position the tRNA anticodon stem-loop correctly in the ADAT2 active site. The ADAT2-ADAT3 complex is required for radial migration of projection neurons in the developing brain cortex, and the catalytic activity of the complex is necessary for this function.
Synonyms: TAD3; FWP005; MRT36; MST121; MSTP121; NEDBGF; S863-5
Gene: Protein-coding gene on chromosome 19 (1,905,399 to 1,913,447, forward strand). Ensembl gene ENSG00000213638.
Subcellular location: Nucleus; Cytoplasm
Subcellular location (Human Protein Atlas): Nucleoplasm
Pathways (Reactome):
Metabolism of RNA: tRNA modification in the nucleus and cytosol
Genetic constraint (gnomAD): Loss-of-function variants: 7 observed, 4.74 expected, observed/expected ratio (o/e) 1.48, 90% interval 0.78 to 1.93. That is too few expected variants to judge how well the gene tolerates losing a copy. Missense variants: 735 observed, 450.72 expected, observed/expected ratio (o/e) 1.63, 90% interval 1.53 to 1.73. Synonymous variants: 358 observed, 217 expected, observed/expected ratio (o/e) 1.65, 90% interval 1.51 to 1.8.
Gene-disease validity (ClinGen):
ClinGen rates the evidence that ADAT3 causes each of these diseases.
intellectual disability-strabismus syndrome (autosomal recessive): Moderate.
Homologues: Orthologues: macaque ADAT3 (98% identical), pig ADAT3 (78% identical), mouse Adat3 (78% identical), mouse Gm49322 (78% identical), rat Adat3 (77% identical), zebrafish adat3 (47% identical), tropical clawed frog minpp1 (40% identical), Drosophila melanogaster CG10927 (29% identical), Caenorhabditis elegans Y47D3A.14 (24% identical). Paralogues in human: ADAT2 (13% identical).
Diseases named in the same sentence as ADAT3 in open-access papers:
ADAT3 is named in the same sentence as 21 diseases in open-access papers, as found by Europe PMC text mining. Sharing a sentence is not in itself a finding about the gene and the disease. The quoted sentences say what the papers report.
Intellectual disability (10 papers, 2015 to 2025). "Inosine enables a single tRNA to recognize and decode multiple synonymous codons, due to its ability to base pair with C, U and G. Patients with ADAT3 mutations exhibit intellectual disability, with the majority also displaying growth delay and microcephaly." (PMID 39723662, 2025). "Although overexpression of ADAT2 has been shown to correct some of the defects in ADAT3 variant patients with intellectual disability, the level of inosine at the tRNA wobble position is tightly regulatedin vivo." (PMID 39034823, 2024). "A missense mutation in ADAT3 (c.382G>A), identified by exome sequencing, is linked to severe intellectual disability." (PMID 37495112, 2023). "Recently, a second mutation in ADAT3—an 8 bp duplication (c.99_106dupGAGCCCGG)—was reported in a patient with mild intellectual disability." (PMID 37495112, 2023). "Point mutations in ADAT3, the partner protein of heterodimeric ADAT, cause intellectual disability and strabismus, and an 8 bp duplication in the ADAT3 gene has been shown to cause mild intellectual disability." (PMID 33921764, 2021). "ADAT3 mutation is a recognized cause of intellectual disability (ID) in Saudi Arabia, particularly amongst consanguineous families." (PMID 34963848, 2021). "A single missense mutation identified in ADAT3 by exome sequencing can cause severe intellectual disability and strabismus, implicating another gene involved in protein translation in the development of neurological diseases." (PMID 30477220, 2018). "Here, we report the second novel ADAT3 mutation in a patient with microcephaly, intellectual disability, and hyperactivity." (PMID 29796286, 2018). "Recently, a second mutation in ADAT3 was reported in a patient with mild intellectual disability." (PMID 30477220, 2018). "We previously reported that a point mutation in ADAT3 causes intellectual disability." (PMID 26416026, 2015). "The constellation of strabismus, dysmorphic facies, intellectual disability, and corpus callosum hypogenesis appears pathognomonic and points to the diagnosis of ADAT3-related disorder." (PMID 40579404, 2025). "Other tRNA modification enzymes that are linked to intellectual disability include the tRNA methyltransferase TRMT1 and NSUN2, thiouridylase CTU2 and the adenosine deaminase ADAT3." (PMID 39723662, 2025). "A founder mutation in the ADAT3 N-terminal domain, which causes intellectual disability, does not affect tRNA binding despite the structural changes it induces but most likely hinders optimal presentation of the tRNA anticodon-stem-loop to ADAT2." (PMID 34057470, 2021).
autosomal recessive intellectual disability (3 papers, 2019 to 2020). "The ADAT3/V144M mutation in humans has been found causative for autosomal-recessive intellectual disability." (PMID 33272269, 2020). "In humans, a valine-to-methionine mutation (V144M) in ADAT3 that originated ∼1,600 years ago is the most common cause of autosomal recessive intellectual disability (ID) in Arabia." (PMID 31263000, 2019). "Exome sequencing and autozygosity mapping have identified a single c.382G>A mutation in the human ADAT3 gene that is causative for autosomal recessive intellectual disability (ID) in multiple families of Saudi Arabian descent (13, –, 15)." (PMID 31263000, 2019).
microcephaly (2 papers, 2018 to 2021). A congenital or acquired developmental disorder in which the circumference of the head is smaller than normal for the person's age and sex. "Individuals with ADAT3 mutation display microcephaly, dysmorphic features, neurological, behavioural, and endocrinal pathologies." (PMID 34963848, 2021).
brain malformation (1 paper, 2025). "Through the GeneMatcher42 and Matchmaker Exchange43,44 platforms, we identified 21 individuals from 18 unrelated families carrying biallelic variants in ADAT3, presenting with IDs and brain malformation." (PMID 40120092, 2025).
cervical carcinoma (1 paper, 2019). A carcinoma arising from either the exocervical squamous epithelium or the endocervical glandular epithelium. "Due to the difficulty in visualizing ADAT3 in LCLs, the localization of ADAT3 was determined by microscopy of HeLa human cervical carcinoma cells transiently expressing ADAT3 fusion proteins with green fluorescent protein at the amino terminus (GFP-ADAT3)." (PMID 31263000, 2019).
Cognitive impairment (1 paper, 2025). Abnormal cognition is characterized by deficits in thinking, reasoning, or remembering. "Biallelic variants in the adenosine deaminase tRNA specific 3 (ADAT3) gene are associated with a distinct neurodevelopmental disorder characterized by dysmorphic facies, poor growth, cognitive impairment, and variable brain anomalies." (PMID 40579404, 2025).
epilepsy (1 paper, 2025). A brain disorder characterized by episodes of abnormally increased neuronal discharge resulting in transient episodes of sensory or motor neurological dysfunction, or psychic dysfunction. "Although epilepsy is not frequently reported in patients with ADAT3 variants, it was found in 5 patients of our cohort (20%)." (PMID 40579404, 2025).
liposarcoma (1 paper, 2025). A usually painless malignant tumor that arises from adipose tissue. "Among the sarcoma group, frequent amplification of ADAT2 and ADAT3 genes is observed in the dedifferentiated liposarcoma (LPS) subset." (PMID 40907939, 2025). "We observed that sarcoma tumors, and specifically liposarcomas, are the cancer types that present the highest level of genetic amplification of the ADAT2 and ADAT3 loci." (PMID 40907939, 2025).
neuroblastoma (1 paper, 2021). Neuroblastoma (NB) is the most common solid, extracranial childhood tumor. "We first verified by transfection experiments in a N2A neuroblastoma cell line that WT ADAT2 and ADAT3 as well as their mutants were similarly expressed." (PMID 34057470, 2021).
Neurodevelopmental delay (1 paper, 2025). "Overall, we expanded the clinical spectrum of ADAT3-related neurodevelopmental disorders by presenting 21 patients displaying severe neurodevelopmental delay associated with heterogenous brain anomalies." (PMID 40120092, 2025).
neuropathy (1 paper, 2025). A disorder affecting the nervous system that manifests with pain, tingling, numbness, and/or muscle weakness. "On the contrary, clubfeet, finger and wrist contractures, neuropathy, bullet-shaped distal phalanges, and feeding difficulties were not spotted in any of our patients, although they were reported in patients with ADAT3 variants." (PMID 40579404, 2025).
recessive intellectual disability (1 paper, 2015). "The mutation we previously reported in ADAT3, for example, is now the single most common cause of autosomal recessive intellectual disability in Saudi Arabia." (PMID 26416026, 2015).
sarcoma (1 paper, 2025). A usually aggressive malignant neoplasm of the soft tissue or bone. "More detailed examination of TCGA datasets revealed that ADAT2 and ADAT3 mRNA expression is elevated in sarcomas compared with normal tissue samples." (PMID 40907939, 2025).
neurodevelopmental disorder (5 papers, 2019 to 2025). A behavioral and cognitive disorder with onset during the developmental period that involves impaired or aberrant development of intellectual, motor, or social functions. "Biallelic variants in ADAT3 are associated with a neurodevelopmental disorder with poor growth, dysmorphic facies, and brain abnormalities (OMIM# 615286)." (PMID 40579404, 2025). "Altogether, our results highlight the critical role of ADAT2/ADAT3 during cortical development and provide cellular and molecular insights into the pathogenic mechanisms underlying ADAT3-related neurodevelopmental disorders." (PMID 40120092, 2025). "Reflecting a key role of I34 modification in brain development, pathogenic variants in ADAT3 have been identified in patients with neurodevelopmental disorders (NDDs)." (PMID 40120092, 2025). "Altogether, these results uncover a potential molecular basis for ADAT3-associated neurodevelopmental disorders in the form of diminished inosine modifications at the wobble position of tRNA caused by ADAT3 misfolding and impaired enzymatic activity." (PMID 31263000, 2019). "First, we report 21 neurodevelopmental disorders patients carrying biallelic variants in ADAT3." (PMID 40120092, 2025). "We further drew an exhaustive list of tRNA species affected in disease conditions, providing strong evidence of a causal relationship between variants in ADAT3, loss of translationally competent ANN tRNAs and neurodevelopmental disorders." (PMID 40120092, 2025). "We describe 24 patients from 16 unrelated Egyptian families with ADAT3-related neurodevelopmental disorder." (PMID 40579404, 2025). "Mutations in ADAT3, the catalytically inactive subunit of the ADAT2/ADAT3 complex, have been identified in patients presenting with severe neurodevelopmental disorders." (PMID 40120092, 2025). "Our study reports a large cohort of patients with ADAT3-related neurodevelopmental disorder from Egypt and reinforces the clinical and brain imaging characteristics of the disorder." (PMID 40579404, 2025). "ADAT3-related neurodevelopmental disorder is very rare with only 60 patients from 29 unrelated families reported in the literature." (PMID 40579404, 2025). "The involvement of ADAT3 in neurodevelopmental disorders suggests under-estimated significance of this accessory subunit to the functions of the deaminase." (PMID 33272269, 2020).
cancer (2 papers, 2021 to 2025). A tumor composed of atypical neoplastic, often pleomorphic cells that invade other tissues. "Taken together, the cancer genetics and mRNA expression data implicate ADAT2 and ADAT3 in various cancers." (PMID 40907939, 2025). "Taken together with our findings that ADAT2 and ADAT3 mRNA expression levels are elevated in most tumor types compared with the corresponding normal tissues we propose that ADAT2/3 is broadly relevant in cancer." (PMID 40907939, 2025). "For ADAT3 and TMEM171, there is little published data on TMEM171 and ADAT3 function in cancer." (PMID 33976744, 2021). "As such, ADAT3 might also be also considered as a potential anti-cancer therapeutic target." (PMID 40907939, 2025). "To explore the requirement for ADAT2/3 in cancer cells, we used short harpin RNA (shRNA) constructs to specifically knock down ADAT2 and ADAT3 expression in human LPS cell lines." (PMID 40907939, 2025).
neurological disorders (1 paper, 2019). "Intriguingly, the perturbed nuclear localization and aggregation into discrete cytoplasmic foci exhibited by the ADAT3-V144M variant are reminiscent of other RNA binding proteins known to misfold and homooligomerize in neurological disorders, such as TDP-43 and TLS/FUS (58, –, 62)." (PMID 31263000, 2019).
tumor (1 paper, 2025). "Moreover, gene copy number analysis showed that ADAT2 and ADAT3 loci are frequently amplified in several tumor types." (PMID 40907939, 2025).
ADAT3 also shares sentences with these, for which no sentence is quoted: Strabismus (2 papers); diffuse large B-cell lymphoma (1); hypospadias (1); rhabdomyosarcoma (1).